HSPB1 (heat shock protein family B (small) member 1)
Diseases named in the same sentence as HSPB1 in open-access papers (continued):
Sharing a sentence is not in itself a finding about the gene and the disease.
glioma (28 papers, 2014 to 2025). A benign or malignant brain and spinal cord tumor that arises from glial cells (astrocytes, oligodendrocytes, ependymal cells). "A novel risk signature containing ferroptosis‐associated HSPB1 has been established and could be used to predict the survival time and radiosensitivity in glioma patients." (PMID 37211949, 2023). "Studies have shown that drugs such as rosmarinic acid and quercetin can effectively silence HSPB1 expression and induce glioma cell apoptosis by activating the caspase‐3 pathway." (PMID 41497799, 2025). "In three datasets from the CGGA database, mRNA_array_301, mRNAseq_325, and mRNAseq_693, the glioma patients with high HSPB1 expression displayed unfavorable survival time." (PMID 37211949, 2023). "Subcellular location showed that HSPB1 mainly exists in the plasma membrane in the U-251 MG glioma cell." (PMID 37158834, 2023). "After then, the UALCAN database was used to confirm the up‐regulation and hypomethylation of HSPB1 in glioma tissues." (PMID 37211949, 2023). "We first explored the expression correlation between FHOD1 and HSPB1 proteins in glioma cohorts from Xiangya Hospital, Central South University." (PMID 37211949, 2023). "In T98G and U251 glioma cells, HSPB1 overexpression suppressed the FHOD1 knockdown‐mediated upregulation of TRF1, a ferroptosis‐positive regulator." (PMID 37211949, 2023). "Mechanically, we found the up‐regulation and hypomethylation of HSPB1, a negative regulator of ferroptosis, in glioma tissues." (PMID 37211949, 2023). "HSPB1 is a small heat shock protein closely associated with the growth and progression of various tumors, such as HCC, colorectal cancer, and glioma." (PMID 37777559, 2023). "First, the CPTAC from the UALCAN database was used to demonstrate that HSPB1 expression was up‐regulated in glioma tissues." (PMID 37211949, 2023). "Collectively, these findings suggested that FHOD1 protected glioma cells against ferroptosis via down‐regulating HSPB1 expression." (PMID 37211949, 2023). "Recent research has indicated that FHOD1 overexpression in glioma attenuates ferroptosis by targeting HSPB1 signaling." (PMID 37723588, 2023). "Colony formation and CCK‐8 experiments both suggested that ectopic expression of HSPB1 obviously blocked the growth‐inhibitory effect of FHOD1 knockdown in glioma cells." (PMID 37211949, 2023). "Silencing of FHOD1 remarkably promoted the ferroptosis sensitivity and growth inhibition in glioma cells through inhibiting heat‐shock protein B (HSPB1)." (PMID 37211949, 2023). "Expression levels of risk factors BRCA1, DNM1L, RCN1, HSPB1, RPN2, LRRK2 and SPP1 in high‐grade gliomas were greater than those in lower‐grade gliomas, while the protein expression levels of protective factor PDIA3 were exactly the opposite." (PMID 33611848, 2021). "HSPB1 correlated with poor outcomes and promoted the proliferation of glioma cells by facilitating an anti‐oxidative response." (PMID 33594759, 2021). "In C6 glioma cells, the chaperone activity of HSPB1 contributed to the production of the pro-inflammatory cytokine, IL-6, whereas T cells from HSPB1−/− mice exhibited reduced secretion of TNF and IL-2." (PMID 33423680, 2021). "The results showed that SLC1A5 was up-regulated in gliomas compared with normal brain tissues in both mRNA and protein levels, and HSPB1 was also overexpressed in glioma samples." (PMID 34726238, 2021). "The protective role of HSPB1 also suggests potential involvement of HSPB1 in chemo-resistance of glioma cells." (PMID 27711253, 2016). "To determine the role of HSPB1 in the proliferation and stress responseof glioma cells, we established stable U87 glioma cells expressing shRNAs against HSPB1." (PMID 27711253, 2016). "SPARC was also reported to promote invasion in gliomas through the up-regulation of the p38 MAPK/MAPKAPK2/HspB1 signaling pathway." (PMID 24514166, 2014). "In gliomas, HspB1 was also described to participate in the signaling pathway that promotes cancer cell survival." (PMID 24514166, 2014).
glioma (continued). "HSPB1 impedes apoptosis in glioma cells by suppressing the activation of caspase‐3." (PMID 41497799, 2025). "The glioma patients with high HSPB1 expression displayed unfavorable survival time." (PMID 37211949, 2023). "Here, we demonstrated the up‐regulated HSPB1 expression in glioma tissues." (PMID 37211949, 2023). "All these findings suggested the depletion of FHOD1 could increase the ferroptosis sensitivity of glioma cells via inhibiting HSPB1 signaling." (PMID 37211949, 2023). "And AKT and PRKG1 were also kinases of HSPB1, which indicated that ipatasertib could be an indirect inhibitor of HSPB1 to enhance glioma ferroptosis." (PMID 37158834, 2023). "The evidence also suggested that macrophage-secreted SPP1 could be an activator of HSPB1 in glioma cells and indirectly inhibit tumor cell ferroptosis." (PMID 37158834, 2023). "FHOD1 knockdown could enhance the ferroptosis sensitivity of glioma cells via up‐regulating the methylated heat‐shock protein B (HSPB1)." (PMID 37211949, 2023). "Moreover, overexpression of HSPB1 in FHOD1‐depleted glioma cells significantly reduced the inhibition of cell growth." (PMID 37211949, 2023). "Ipatasertib showed a lower IC50 value in high-HSPB1 glioma cells than in low-HSPB1 glioma cells." (PMID 37158834, 2023). "Moreover, the expression levels of HSPB1 were found significantly reduced in FHOD1‐depleted glioma cells T98G and U251." (PMID 37211949, 2023). "HSPB1 also enhances proliferation via SIRT2-mediated G6PD activation in glioma cells." (PMID 32733879, 2020). "For instance, high expression of HSPB1 is correlated with a low survival rate in glioma patients." (PMID 32733879, 2020). "Additionally, we investigated two TCGA cohorts (glioblastoma and brain low-grade glioma) and found that high HSPB1 expression correlated with poor overall survival rate (p = 0.0034 for TCGA glioblastoma multiforme; p = 0.0004 for TCGA Brain Low Grade Glioma)." (PMID 27711253, 2016). "Notably, HSPB1 was expressed at basal level in normal cells, whereas glioma cells expressed very high levels of HSPB1." (PMID 27711253, 2016). "High expression of HSPB1 correlates with poor survivalrate of glioma patients." (PMID 27711253, 2016). "Together, these data indicate that HSPB1 sustains G6PD activity in glioma cells." (PMID 27711253, 2016). "HSPB1 overexpression was considered to impair the efficiency of chemotherapy in glioma." (PMID 27711253, 2016). "Macrophage-secreted SPP1 could be a potential activator for HSPB1 in glioma cells." (PMID 37158834, 2023). "In addition, HSPB1 was overexpressed in FHOD1‐deficient T98G and U251 glioma cells." (PMID 37211949, 2023). "Finally, we recognized that ipatasertib, a novel pan-Akt inhibitor, could be a potential drug for suppressing HSPB1 phosphorylation, inducing ferroptosis of glioma cells." (PMID 37158834, 2023). "Moreover, the pro‐ferroptotic effects of FHOD1 knockdown in glioma cells could be effectively impaired by HSPB1 overexpression in vitro and in vivo." (PMID 37211949, 2023). "Thus, HSPB1 potentially contributes to the tumorigenesis and development of glioma." (PMID 27711253, 2016). "HSPB1 might function as a chaperone and protect glioma cells from stressed conditions." (PMID 27711253, 2016). "Thus, suppression of HSPB1 possibly sensitizes glioma cells to alkylating reagents." (PMID 27711253, 2016). "Pearson correlation analysis indicated the positive correlation between FHOD1 expression and HSPB1 expression in both glioblastoma multiforme (GBM) and lower‐grade glioma (LGG) tissues." (PMID 37211949, 2023). "Immunohistochemical staining revealed that five genes (ZEB1, CA9, HSPb1, STAT3, and TNFAIP3) had a higher expression in glioma tissues than in normal tissues." (PMID 35711838, 2022). "The T cell depletion-related prognostic model was developed based on seven prognostic genes (HSPB1, HOXD10, HOXA5, SEC61G, H19, ANXA2P2, HOXC10) in glioma." (PMID 36531217, 2022).
glioma (continued). "Higher HSPB1 was found to contribute to glioma development, while CBS expression, consistent with our results, was reduced in glioma progression." (PMID 34819946, 2021). "HSPB1 activates G6PD by promoting SIRT2-mediated G6PD deacetylation, thereby contributing to glioma cell survival and proliferation." (PMID 27711253, 2016). "In this study, we demonstrated that HSPB1 sustained cellular NADPH and pentose production in glioma cells." (PMID 27711253, 2016). "In conclusion, our study revealed that HSPB1-mediated G6PD activation sustained cellular NADPH and pentose levels, and promoted glioma cell proliferation and survival." (PMID 27711253, 2016). "Furthermore, BMP2, NCF1, HSPB1, PIGT, PTX3, CCNA2, and CCNB2 exhibited increased expression, while DES displayed decreased expression in glioma tissues." (PMID 40656950, 2025). "HSPB1 enhanced SIRT2-mediated G6PD activation and promoted glioma cell proliferation." (PMID 36566214, 2022). "Moreover, ZEB1, CA9, HSPB1, STAT3 and TNFAIP3 of the overlapping genes were upregulated in glioma tissues." (PMID 35711838, 2022). "For certain HSPs representatives (i.e., HSP10, HSPB1, DNAJC10, HSPA7, HSP90), a direct correlation between the protein level expression (based on IHC analysis) and poor overall survival prognosis for patients with glial tumors was identified." (PMID 36358853, 2022). "Furthermore, we explored the mRNA expression levels of SLC1A5 and HSPB1 in the GEPIA website and the protein expression levels using clinical samples between normal brain tissues and gliomas." (PMID 34726238, 2021). "As HSPB1 contributes to glioma cell growth and survival through regulating SIRT2-G6PD interaction, the relationship between HSPB1 expression and the development of glioma, merits further explorations." (PMID 27711253, 2016). "HSPB1 activatedG6PD, the first and rate-limiting enzyme of pentose phosphate pathway, through enhancing SIRT2-mediated deacetylation of G6PD, hence protected glioma cells from oxidative stress and DNA damage." (PMID 27711253, 2016). "Besides, HSPB1 activates G6PD to sustain cellular NADPH and pentose production in glioma cells." (PMID 27711253, 2016). "Similarly, knockdown of either G6PD or HSPB1 sensitized glioma cells to oxidative reagents (H2O2 or diamide), but no additive effect was found in HSPB1- and G6PD-knockdown cells." (PMID 27711253, 2016). "Very recently, HSPB1 was reported to activate glucose 6-phosphate dehydrogenase (G6PD), the rate-limiting enzyme in pentose phosphate pathway, in response to oxidative stress (.These observations indicate that HSPB1 possibly regulates the metabolism of glioma cells." (PMID 27711253, 2016). "However, previous studies of CAPG, FANCD2, HMOX1, HSPB1, RRM2, and STEAP3 did not develop any new clinical therapy in glioma." (PMID 36566214, 2022).
prostate carcinoma (24 papers, 2009 to 2024). A carcinoma that arises from epithelial cells of the prostate gland. "It is reported that high levels of HSPB1 in prostate cancer are associated with poor clinical outcomes, as HSPB1 expression results in tumor invasion and metastasis." (PMID 34578333, 2021). "The interaction term of CCND2*HSPB1 was added to the model because combined methylation of both genes together was negatively associated with death from prostate cancer." (PMID 27708246, 2016). "The functional relationship between Hsp-27, encoded by the gene HSPB1 located on human chromosome 7 at q11.23, and behavioural phenotype was suggested in the preliminary study that showed Hsp-27 expression to predict (P<0.0001) death from prostate cancer." (PMID 19707199, 2009). "Downregulation of HSPB1/Hsp27 expression by RNA interference increased the expression of a key AJ protein, E-cadherin, in colorectal, pancreatic ductal, and prostate cancer cells." (PMID 38474334, 2024). "Previous studies have shown that HSPB1 exerted a tumor-promoting effect in various cancers through its proliferative and anti-apoptotic functions, such as esophageal squamous cell, prostate cancer, carcinoma squamous cell carcinoma of tongue." (PMID 37454220, 2023). "Consistently, digitoxin is also able to significantly suppress mRNA expression for both HSPB1, a biomarker for EMT in prostate cancer, and the HSPB1/RBFOX2 ratio." (PMID 31428571, 2019). "The eight proteins highlighted in this study (KLK3, SORD, SPON2, IMPDH2, ACTN4, ATP1B1, HSPB1, and KHDRBS1) represent a signature associated with AR modulation during the transition from androgen-dependent to castration-resistant prostate cancers." (PMID 29966326, 2018). "Previous literature indicated that these six genes, i.e., CAV1, COL4A2, HSPB1, ITGB3, MAP1A and MCAM, were linked to prostate cancer progression." (PMID 26158290, 2015). "In prostate cancer, HspB1 also appears as an important player that promotes EMT since its depletion is associated with decreased cell migration, invasion, and MMP-2 activity." (PMID 24514166, 2014). "A study performed in prostate cancer showed that HspB1 up-regulation, which is particularly intense after androgen withdrawal, confers broad-spectrum treatment resistance including chemotherapy." (PMID 24514166, 2014). "Another study suggested that the expression of HSPB1 may be used to predict poor prognosis and transfer tendency in prostate cancer and demonstrated that HSPB1 was promoted in an insulin-like growth factor 1-dependent manner." (PMID 37268925, 2023). "In addition, HSPB1 expression in prostate cancer cells is significantly increased after androgen deprivation and chemotherapy and acts as a molecular chaperone for cell protection, making cells resistant to drugs." (PMID 37268925, 2023). "Recent research has found that erastin could enhance the expression of HSPB1 mRNA and protein and that the HSF1‐HSPB1 pathway could negatively regulate erastin‐induced ferroptosis in human cervical cancer cells, osteosarcoma cells and prostate cancer cells." (PMID 27860262, 2017). "Our results showing that hspB1 directly regulates cell proliferation are in agreement with two recent reports showing that hspB1 silencing by RNAi inhibits tumour growth and a prostate cancer cell proliferation." (PMID 24143227, 2013). "Additionally, HSPB1-induced prostate cancer cell motility and metastatic progression." (PMID 37010714, 2023). "Our findings support the original hypothesis that methylation status of six selected index genes (HSPB1, CCND2, TIG1, DPYS, PITX2, and MAL) provides a novel, objective, and accurate prediction of death from prostate cancer in men clinically assessed as low to intermediate risk." (PMID 27708246, 2016).
prostate carcinoma (continued). "However, multivariate analysis revealed that methylation of DPYS, CCND2 and HSPB1 together added a substantial amount of prognostic information not captured by any other measure and therefore may be useful for improvement of prostate cancer management." (PMID 25193387, 2014). "Similarly to HSPB1, CCND2 methylation displayed an HR of 0.86 [95% CI 0.75-0.98] indicating that higher levels of methylation were associated to lower risk of prostate cancer death, consistent with the role of activated CCND2 as an oncogene." (PMID 25193387, 2014). "In a recent report, we demonstrated that changes in methylation of HSPB1, CCND2, TIG1, DPYS, and, MAL, had significant prognostic effects in multivariate Cox models where death from prostate cancer was the study endpoint." (PMID 27708246, 2016). "Methylation was quantified by pyrosequencing assays for six genes (HSPB1, CCND2, TIG1, DPYS, PITX2, and MAL) with established biomarker value in prostate cancer." (PMID 27708246, 2016). "Recently, it was reported that differential methylation of DPYS (and heat shock 27 kDa protein 1, HSPB1, OMIM: 602195 and cyclin D2, CCND2, OMIM: 123833) provides independent prognostic information for prostate carcinoma." (PMID 27733154, 2016). "In this study, we selected six genes, that had additionally been independently reported to be related to prostate cancer progression, CAV1, COL4A2, HSPB1, ITGB3, MAP1A and MCAM." (PMID 26158290, 2015). "A model including PSA, and methylation of DPYS, HSPB1, MAL and TIG1 was better at predicting prostate cancer-related mortality than a model based only on gene methylation." (PMID 25193387, 2014). "Assays measuring methylation of MAL, TIG1, HSPB1, CCND2, and DPYS have potential to accurately stratify early prostate cancers and thereafter to manage affected patients in a biologically appropriate manner." (PMID 25193387, 2014). "In the comprehensive multivariate analysis, the model with best prognostic ability included Gleason score, PSA, HSPB1, [HSPB1xGleason score], CCND2 and DPYS demonstrating that gene methylation added significant information for predicting prostate cancer-related death." (PMID 25193387, 2014). "Conversely, the CEMIP, HSPB1, and PANX2 genes, which interfere with the process of ferroptosis, can effectively promote the survival of prostate cancer cells, suggesting that ferroptosis-related genes may be prognostic biomarkers and potential drug targets for patients with prostate cancer." (PMID 38705987, 2024).